MTOR (mechanistic target of rapamycin kinase)
Diseases named in the same sentence as MTOR in open-access papers (continued):
Sharing a sentence is not in itself a finding about the gene and the disease.
cancer (continued). "Disruption of the tightly regulated PI3K/AKT/mTOR signaling induced by genetic alternations in cancer leads to growth advantages and common cancer-associated patterns such as accelerated cell growth without negative feedback, increased survival and metastatic potential." (PMID 32962206, 2020). "Indeed, increased mTOR nuclear localization has been associated with poor prognosis in patients with different types of cancer." (PMID 32325714, 2020). "In addition, PI3K/Akt/mTOR pathway activation is one of the main causes of cancer cell resistance to antitumour therapies." (PMID 32211045, 2020). "More than 30 activating mutations of mTOR have been reported in human cancer." (PMID 32131492, 2020). "Reduced mTOR ubiquitination is also linked to therapy resistance in cancer." (PMID 33004065, 2020). "mTOR mediated resistance can occur in a cell-autonomous manner through the MAPK pathway or in a non-cell autonomous manner by dynamic rewiring of molecular signals that cause emergence of resistance to proximal cancer cells." (PMID 33082316, 2020). "First, we analyzed the impacts of mTOR inhibition on MET-deficient cancer cells." (PMID 32764535, 2020). "On the other hand, the alterations in SNP and INDEL distribution and gene fusion could affect the epigenetic and metabolic process by activating a series of cancer-associated cascades (Wnt, mTOR, Hippo, Notch, VEGF)." (PMID 32054519, 2020). "Furthermore, Rab escort protein 1 (REP1) is associated with cancer progression by contributing to cell growth and survival through the regulation of mTOR signaling and its downstream pathways." (PMID 33195279, 2020). "Aberrant regulation of mTOR is a hallmark of many cancers, including hematological malignancies." (PMID 33489922, 2020). "Studies have found that E3 ligase TRAF6, which is upregulated in cancer cells, can mediate K63-linked polyubiquitination of mTOR by interacting with p62 under the stimulation of amino acids, promoting the translocation of mTORC1 to the lysosomes and subsequent activation." (PMID 33004065, 2020). "Mutations in mTOR signalling pathways are present in cancer cell growth and development." (PMID 33479617, 2020). "Additionally, we examined the role of circadian clock genes in cancer-related hallmark pathways such as TSC/mTOR, RTK, RAS/MAPK, PI3K/AKT, Hormone ER, Hormone AR, EMT, DNA Damage Response, Cell Cycle, and Apoptosis pathways." (PMID 32681792, 2020). "KEGG pathway analyses revealed these CRPs to be enriched for key cellular pathways including “pathway in cancer”, “Rap1 signaling”, “mTOR signaling” and “MAPK signaling”, which are closely linked to cell proliferation, cell migration, apoptosis, and the cell cycle." (PMID 32293333, 2020). "In turn, silencing of Orai1 and 2 with SOCE chemical inhibitors and siRNAs inhibits calcium uptake and suppresses cancer cell proliferation, colony formation, and migration in association with inhibition of the Akt/mammalian target of rapamycin (mTOR)/nuclear factor κB (NF-κB) pathway." (PMID 33511135, 2020). "Recently, studies have indicated that the PI3K/AKT/mTOR pathway may be commonly activated in multiple human cancers by molecular abnormalities such as PIK3CA mutations." (PMID 33344221, 2020). "Overall, utilizing agents that target both Akt and mTOR, causing both a reduction in the phosphorylated/activated and total levels of these proteins, may result in cancer cells becoming more sensitized to treatments and reducing drug resistance." (PMID 32012648, 2020). "Mutations of closely related pathways have enhanced mTOR signaling in cancers." (PMID 31075885, 2019). "The PI3K/Akt/mTOR pathway is up-regulated in cancer due to several mechanism including activating mutations of PI3K and Akt, inactivating mutations of PTEN and over-expression of upstream receptors such as the tyrosine kinase human epithelial receptor family (HER)." (PMID 30056610, 2019).
cancer (continued). "Notably, the PI3K/AKT/mTOR pathway is not only important for the phenotypic response of hypoxic HPV-positive cancer cells where the hypoxia-linked inhibition of mTORC1 signaling impairs their senescence response." (PMID 31058807, 2019). "Of particular note, the mechanisms underlying the varied responsiveness to mTOR inhibitors in cancer patients may be complex." (PMID 31277692, 2019). "Alternatively, combined inhibition of wee1, a protein kinase that regulates the G2 checkpoint in the cell cycle, with mTOR inhibition may selectively treat RAS-mutated cancer." (PMID 31277692, 2019). "As such, 45S rDNA copy number reduction in cancer is associated with mTOR activation and may prove to be a simple way to determine if a cancer will be susceptible to DNA-damaging treatments." (PMID 31338556, 2019). "However, in case of drug-resistant cancer patients with activating mTOR mutations, for those who acquire resistance to first generation inhibitors of mTOR, a second generation of inhibitors that targets the kinase domain (TORKIs) has been developed." (PMID 31277491, 2019). "In addition, we discuss the mechanisms underlying the resistance to mTOR inhibitors in cancer cells." (PMID 31277692, 2019). "Importantly, the mTOR inhibitor medications failed in clinical cancer therapy owing to the heterogeneity and mutation of mTOR." (PMID 31557936, 2019). "In addition to Akt signaling, mTOR signaling has been associated with the acquisition of X-ray resistance in cancer cells." (PMID 31799186, 2019). "Hence, mTOR inhibitor–based regimens have been usedde novo to prevent cancer development in transplant patients with high cancer risk and conversion to an mTOR inhibitor–based regimen is often considered if cancer is diagnosed." (PMID 30828430, 2019). "Specifically, a study identified 33 MTOR mutations that lead to pathway hyperactivity in cancer." (PMID 30764584, 2019). "Moreover, genetic lesions can also promote the activation of the PI3K/mTOR pathway in cancer cells, such as those encoding for Ras, Akt, TSC1/2, Notch1, and receptor tyrosine kinases." (PMID 31817676, 2019). "Mutations in mTOR itself are observed in various cancer subtypes." (PMID 30857853, 2019). "mTORC1 plays the major role in the regulation of the mitochondrial protein translation, moreover mTOR is an important regulator of mitochondrial turnover by regulating mitochondrial fusion and fission processes mainly deregulated in cancer and that are associated with chemotherapy resistance." (PMID 31921637, 2019). "The aberrant activation of mTOR in human cancer may be attributed to mTOR pathway-activating mutations, amplification, or overexpression of the components of mTOR complexes and mutations or loss of negative regulators of mTOR." (PMID 31277692, 2019). "JPH203 is a tyrosine analog and thus competitively inhibits LAT1 transporter functions in several types of cancer cells to attenuate their migration/invasion activities and induce apoptosis, which has been thought to be associated with inactivation of the mTOR signaling pathway." (PMID 31748583, 2019). "Furthermore, the activation of the PI3K/Akt/mTOR pathway has been implicated in the pathogenesis and chemoresistance of cancer." (PMID 31354479, 2019). "mTOR has emerged as an important regulator of nucleotide metabolism and is implicated in multiple human cancer types." (PMID 30857853, 2019). "Moreover, it is well-known that PI3K/Akt/mTOR and NF-κB pathways have not only been implicated in carcinogenesis but also in cancer cell invasion and the metastatic process." (PMID 31658635, 2019).
cancer (continued). "In particular, the T>A mutation in chr1:11169377, which resulted in a p.I2500F change on protein sequence, activates the PI3K–AKT–mTOR signalling pathway and causes mTOR complex 1 (mTORC1) signalling to be partially resistant to nutrient deprivation in cancer cells." (PMID 30380109, 2019). "mTOR pathway regulates the cell growth which is associated with energy, nutrients, growth factors and other environmental conditions, and it plays a prominent role in cancer." (PMID 30787203, 2019). "The link between the mTOR pathway and beneficial health effects is supported by a large number of studies, demonstrating that inhibition of this cell signaling pathway is associated with health benefits such as anti-cancer and anti-inflammatory effects." (PMID 30679557, 2019). "Moreover, TMP21 inhibits mTOR- and PKCδ-mediated apoptosis in cancer cells, while dysfunction of mTOR- and PKCδ is implicated in synaptic impairment and neuronal apoptosis." (PMID 31379512, 2019). "Combination of RAF/MEK inhibitors and mTOR inhibitors may be a strategy to treat KRAS-mutated cancer." (PMID 31277692, 2019). "Additionally, recurrent genetic aberrations in specific components of the two distinct mTOR complexes have been reported in association with cancer." (PMID 29351204, 2018). "Since mTOR signalling controls both cell growth and proliferation and since activating mutations of components of this pathway are frequently found in cancer, many studies addressed the effects of mTOR inhibitors in cancer therapy." (PMID 30061533, 2018). "Notably, Rapa-Link1 is effective against tumor cells which harbor mTOR mutations that render them resistant to rapalogs and active-site mTOR inhibitors and has shown promising results in preclinical cancer models." (PMID 29610153, 2018). "Also, top KEGG pathway analysis results exhibit some pathways that have a known association to breast and other cancers such as mTOR, Oxytocine, MAPK, AGE-RAGE signaling pathways." (PMID 30206342, 2018). "Cancer cell growth and survival are associated with mTOR signalling activity." (PMID 30544833, 2018). "Although, further works are required to clarify the roles of O-GlcNAcylation on PI3K/AKT/mTOR regulation under normal physiological context, their interplay is highlighted by their associated dysregulation in several types of cancer, T2D, and cardiovascular and neurodegenerative diseases." (PMID 30356686, 2018). "Furthermore, AMPK activation has been implicated in suppressing anabolic signaling in cancer cachexia by inhibiting mTOR." (PMID 29844217, 2018). "Indeed, mutations of PDK1, PTEN, or Akt have been discovered in cancer, which affect Akt or mTOR signaling." (PMID 30406111, 2018). "In addition, the PI3K–Akt–mTOR pathway is associated with many oncogenic processes and is one of the most frequently dysregulated signaling pathways in cancer, including hypopharyngeal cancer." (PMID 29760955, 2018). "However, in various diseases, especially in cancer, this capacity is lost because of mutations or activation of signals upstream of mTOR that lead to persistent proliferation and tumor growth." (PMID 29329543, 2018). "PI3K-Akt-mTOR signaling is associated with the balance between cell proliferation and survival and plays a major role not only in tumor growth but also in the potential response of cancer treatment, such as wortmannin and LY294002." (PMID 30154914, 2018). "We previously demonstrated that PKD is significantly associated with the risk of cancer, within which mTOR may play an important role." (PMID 29751520, 2018).
cancer (continued). "Aberrant mTOR signalling in cancer is commonly caused by either loss of function mutations of upstream tumour suppressor proteins or activating mutations within oncogenes that feed into the mTOR pathway." (PMID 29301334, 2018). "Mutations occurred in multiple cancer types, with one of the reported clusters being particularly prominent in kidney cancer and conferring pathway hyperactivation and, potentially, sensitivity to targeted therapies directed against mTOR." (PMID 29351204, 2018). "Another hallmark of cancer cells is the requirement of leucine for mTOR activation in lysosome." (PMID 29988369, 2018). "Although uncommon, activating mutations within the kinase domain of mTOR occurs in cancer." (PMID 30308940, 2018). "Hence, impaired mTOR activity has been associated in widespread human diseases, including cancer, type 2 diabetes, cardiovascular pathology, and neurodegeneration as well as during aging." (PMID 30510618, 2018). "The key role of mTOR in these processes explains its association in pathologies such as cancer." (PMID 29707520, 2018). "Although the constitutive activation of the mTOR gene can occur, mutations in downstream and upstream components of both mTORC1 and mTORC2 are more frequent, and these mutations are responsible for inducing cancer cell growth, survival, and proliferation." (PMID 29932116, 2018). "Consequently, dysregulation of the mTOR pathway is often associated with a variety of disease, such as cancer and metabolic and genetic disorders." (PMID 29772672, 2018). "Additionally, the PI3K/AKT/mTOR pathway is associated with various oncogenic processes, and is one of the signaling pathways most frequently dysregulated in cancer, including OSCC." (PMID 30423811, 2018). "The mTOR signaling pathway is a well-known cancer-associated pathway." (PMID 29666752, 2018). "Several reasons may explain the limitations of targeting mTORC1 in cancer therapy—resistant mutations of mTOR, activation of alternate proliferative signaling pathways, and intratumoral heterogeneity of mTOR activity, among others." (PMID 30326670, 2018). "Finally, the other three pathways, Hippo signaling pathway, Neurotrophin signaling pathway and mTOR signaling pathway are associated with cancer in general." (PMID 29666752, 2018). "Several cancer cell lines have been characterized by having mutations in the mTOR pathway." (PMID 30359271, 2018). "Firstly, mTOR inhibitors, similar to many other cancer precision therapeutic options, may cause programmed cancer cell death." (PMID 28822012, 2017). "We then tested whether in cells expressing cancer-associated hyperactivating MTOR mutations, BC-LI-0186 could still inhibit the mTORC1 pathway through LRS interactions." (PMID 28963468, 2017). "But one of the most frequently implicated modes of cancer cell resistance is the ability of IGF-IR to enhance PI3K/AKT/mTOR signaling, which could bypass the effects of the therapeutic agents." (PMID 27661006, 2017). "Numerous studies have shown the association between PLCE1 and PI3K/AKT/mTOR signaling during inflammation-association carcinogenesis, thus targeting PI3K/AKT/mTOR-mediated inflammatory pathway could be a good strategy for cancer prevention and therapy." (PMID 28402280, 2017). "Suppression of mTOR results in damage and loss of mitochondria in cancer." (PMID 28373964, 2017). "Loss of 4E-BP1 expression has been linked to cancer progression and resistance to mTOR inhibitors, but the mechanism underlying 4E-BP1 downregulation in tumors remains unclear." (PMID 29263324, 2017).
cancer (continued). "Additionally, the growth factor receptors IGFR and EGFR, which cause PI3K-Akt-mTOR pathway activation and foment cancer cell proliferation were also downregulated upon TH588-treatment." (PMID 28542590, 2017). "Moreover, mTOR activation appears to be associated with cancer cell invasion and metastasis in solid tumors." (PMID 28831205, 2017). "The data indicated that no publication bias might have a significant influence on the observed effect of SNPs located at pTEN/AKT/mTOR pathway on the susceptibility of cancer as assessed." (PMID 29259266, 2017). "Up to now, only two meta-analyses focused on mTOR rs2295080 polymorphism and cancer risk." (PMID 29259266, 2017). "Therefore, considering the critical role of the genetic variations in the pTEN/AKT/mTOR pathway, understanding the association between these SNPs and cancer susceptibility are urgently required." (PMID 29259266, 2017). "In addition, mTOR activation appears to be associated with cancer cell invasion and migration in solid tumors." (PMID 28831205, 2017). "Mutations in the genes encoding for the proteins of mTOR associated BRN can lead to different types of cancers including sporadic cancers, hamartoma syndromes or phakomatoses, cowden syndrome (PTEN), neurofibromatosis (NF1, NF2) and peutz–Jeghers syndrome (LKB1)." (PMID 28659828, 2017). "In fact, BAP1 mutations in tumors are associated with pathological features of aggressive disease including high Fuhrman grade, metastatic disease at presentation, worse cancer specific survival, instantaneous activation of mTOR signaling, and activation of pathways implicated in growth factors." (PMID 28812986, 2017). "Therefore, this comprehensive meta-analysis was performed in 5 SNPs of pTEN/AKT/mTOR pathway genes included all eligible case-control studies for evaluating the cancer risk and providing more precise estimation of these associations." (PMID 29259266, 2017). "Several reports have demonstrated that S1P could induce mTOR activation in several cancer cell lines associated with fibroblasts and vascular smooth muscle cells." (PMID 29186197, 2017). "It was found that phosphorylated MTOR (p-MTOR) was more highly expressed in limited-stage than extended-stage SCLCs, and higher p-MTOR expression was associated with better prognosis, in contrast to other cancers." (PMID 28280736, 2017). "Abnormal induction of mTOR signaling has been implicated in several cancers." (PMID 28658303, 2017). "Cancer genomes with lower copies have mutational evidence of mTOR hyperactivity." (PMID 28640831, 2017). "Compared to normal cells which depend on nutrient signals to inactivate ECHS1 and to trigger the anabolic metabolism, cancer cells may trigger anabolic metabolism by gaining mTOR activating mutations or ECHS1 inactivating mutations." (PMID 28878358, 2017). "Besides loss of function of autophagy in cancer cells, increased survival and proliferative signals, such as PI-3 kinase and mTOR, render them less able to induce autophagy." (PMID 29212227, 2017).